STAT4 (signal transducer and activator of transcription 4)
Diseases named in the same sentence as STAT4 in open-access papers (continued):
Sharing a sentence is not in itself a finding about the gene and the disease.
influenza (5 papers, 2010 to 2023). An acute viral infection of the respiratory tract, occurring in isolated cases, in epidemics, or in pandemics; it is caused by serologically different strains of viruses (influenzaviruses) designated A, B, and C, has a 3-day incubation period, and usually lasts for 3 to 10 days. "Combining splenocytes from IFNAR+/− or IFNAR−/− (CD45.2+) mice with splenocytes from B6 WT (CD45.1+) mice in vitro, followed by infection with flu yielded similar results, i.e. STAT4 was activated to an intermediate level in IFNAR−/− NK cells." (PMID 23300570, 2012). "Thus, IL-10 becomes induced in IFN-γ+CD4+ T cells during influenza by IL-27, in part mediated via STAT4." (PMID 24809349, 2014). "The seemingly apparent lack of effect of STAT4−/− in HSV-1 infection most likely indicates immune compensation orchestrated by STAT4-independent pathways or differences in response from the triggering antigen as seen during influenza infection of STAT4−/− mice and in autoimmune diabetes." (PMID 20104254, 2010). "In contrast to STAT1−/− NK cells, STAT4−/− NK cells were defective for IFN-γ production, but displayed WT levels of granzyme B induction following influenza infection." (PMID 23300570, 2012).
Insulin resistance (5 papers, 2017 to 2022). Increased resistance towards insulin, that is, diminished effectiveness of insulin in reducing blood glucose levels. "STAT4 deficiency in CD8+ cells ameliorates insulin resistance and chemokine production in adipocytes and islets and improves β-cell function." (PMID 28400678, 2017). "Studies have shown that the deficiency of STAT4 in high-fat diet-fed mice in T2DM mice was associated with reduced adipose tissue inflammation and decreased insulin resistance." (PMID 32851081, 2020). "Collectively, our data emphasize that STAT4 in hematopoietic cells plays a key role in adipose tissue inflammation and insulin resistance." (PMID 28400678, 2017). "Studies in Rag1−/− mice further confirmed the prominent role of CD8+ cells expressing STAT4 in insulin resistance and AT and islet inflammation." (PMID 28400678, 2017). "Future studies will help to address further details of the molecular mechanisms responsible for STAT4 involvement in the pathogenic role of CD8+ cells in adipose tissue inflammation and insulin resistance." (PMID 28400678, 2017). "Adipose tissue macrophages are important contributors to insulin resistance and STAT4 was shown to be required for M1 macrophage polarization and IFNγ production in response to IL12/18." (PMID 28400678, 2017). "In this study, we further investigated the role of STAT4 in different T cell subsets on insulin resistance and inflammation using a Rag1−/− model of diet-induced obesity." (PMID 28400678, 2017). "We have also reported that STAT4 is a mediator of meta-inflammation and insulin resistance in adipose tissue in obesity and has been shown to have increased expression in injured lesions in blood vessels of diabetic rats." (PMID 28107529, 2017). "In this study we investigated selective STAT4 deficiency in hematopoietic cell subsets as well as in cells from the nonhematopoietic compartment (adipocytes) on insulin resistance and adipose tissue inflammation in diet-induced obesity." (PMID 28400678, 2017). "Also, we reported that STAT4 global deletion reduces insulin resistance and adipose tissue inflammation in obesity in part by reducing adipocyte hypertrophy, infiltration of immune cells, by promoting M2-biased macrophage polarization, and by improving insulin signaling in adipose tissue." (PMID 28400678, 2017). "The mechanism may involve TLR4 activation in macrophages as it was shown that TLR4 requires STAT4 for IFNγ production in response to IL12 and ablation of TLR4 in the myeloid compartment prevents insulin resistance in obese mice." (PMID 28400678, 2017).
liver disease (5 papers, 2012 to 2023). "This difference in the underlying cause of HCC reflects the different mechanisms of HCC development and the role of STAT4 in its occurrence in different etiologies of liver disease." (PMID 37760499, 2023). "STAT4 therefore represents a potential therapeutic target to induce NK cell tolerance in liver disease." (PMID 26887815, 2017). "Genes of inflammation and immunity (CD276, CDH6, GCKR, HNF1A, HPR, ITGA1, RORA, and STAT4) have been shown to be expressed in liver disease patients." (PMID 22530132, 2012). "For instance, the role of STAT4 in HCC development may differ depending on the etiology of liver disease." (PMID 37760499, 2023). "We found that STAT4 was constitutively phosphorylated to greater levels in PBC than in the liver disease controls, and of functional relevance NK cells in PBC could be induced to secrete more IFNγ." (PMID 31803181, 2019).
melanoma (5 papers, 2015 to 2025). A malignant, usually aggressive tumor composed of atypical, neoplastic melanocytes. "Here, our results indicate that IL-12 provided an intrinsic survival advantage to B16 melanoma cells and acted directly on B16 melanoma cells to phosphorylate Akt, which is in contrast to the canonical phosphorylation of STAT4 in T helper cells." (PMID 32450888, 2020). "Moreover, activation of antigen-presenting cells in the murine B16F10 melanoma model stimulates the IL-12/STAT4 signalling pathway." (PMID 40868162, 2025).
Obesity (5 papers, 2017 to 2024). Accumulation of substantial excess body fat. "Although there is evidence that STAT4 is involved in cardiovascular diseases, the potential role of STAT4 in obesity VT risk is unknown." (PMID 39063055, 2024). "Collectively our results show specific and dominant contribution of STAT4 in the hematopoietic compartment to metabolic health and inflammation in diet-induced obesity." (PMID 28400678, 2017). "Our group recently reported expression of STAT4 in adipocytes and increased STAT4 activation in visceral adipose tissue in rodent obesity." (PMID 28400678, 2017). "Our findings further suggest suppression of STAT4 activation may protect against ventricular pathology, representing a novel therapeutic approach for VT/SCD predisposition in obesity." (PMID 39063055, 2024). "Although the total numbers of CD11b+F4/80+ cells were not different in adipose tissue between the two groups, it is possible that STAT4-sufficient BM macrophages that migrated into AT in response to obesity were more proinflammatory compared to the Stat4−/− BM." (PMID 28400678, 2017). "Also, we previously showed that in diet-induced obesity mice with global STAT4 deletion have similar macrophage numbers compared to wild-type mice; however, there were a significantly increased proportion of the CD11b+F4/80+CD206+ cells, indicating a bias towards the M2 phenotype." (PMID 28400678, 2017).
uveitis (5 papers, 2013 to 2025). An inflammatory process affecting a part of or the entire uvea. "Genotype and minor allele frequencies of IL23R and STAT4 genetic variants in uveitis patients and healthy controls." (PMID 24312163, 2013). "Genome-wide association studies (GWASs) have provided a powerful tool for the genome-wide analysis of genetic susceptibility to uveitis, revealing several genes associated with uveitis, including IL23R/C1ORF141, STAT4, and ADO/ZNF365/Egr2." (PMID 34869347, 2021). "In addition, genome-wide association studies revealed that abnormities of many non-HLA genes such as the interleukin (IL) family and the Signal transducer and activator of transcription 4 (STAT4) also participate in the progression of uveitis." (PMID 28505077, 2017).
acute myeloid leukemia (4 papers, 2023 to 2024). Acute myeloid leukemia (AML) is a group of neoplasms arising from precursor cells committed to the myeloid cell-line differentiation. "The aim of our study is to explore the mechanism of transcription-4 (STAT4) in acute myeloid leukemia (AML)." (PMID 38737443, 2024).
Cognitive impairment (4 papers, 2022 to 2026). Abnormal cognition is characterized by deficits in thinking, reasoning, or remembering. "IL-12 activates STAT4 to regulate myeloid cell functions, and blockade of this pathway alleviates cognitive impairment in Alzheimer's models." (PMID 41929047, 2026).
head and neck squamous cell carcinoma (4 papers, 2020 to 2024). A squamous cell carcinoma that arises from any of the following anatomic sites: lip and oral cavity, nasal cavity, paranasal sinuses, pharynx, larynx, and salivary glands. "The accumulation of MDSCs and systemic depletion of Th17 cells and IL‐17 were also attributed to STAT4 deficiency in head and neck squamous cell carcinoma." (PMID 38107057, 2023). "In head and neck squamous cell carcinoma, however, STAT4 mediates resistance to metastasis, and activation of STAT4 could potentially mitigate lymphatic metastasis." (PMID 38611065, 2024).
liver cirrhosis (4 papers, 2013 to 2023). "The STAT4 rs7574865 T allele and HLA-DR *04 allele for the progression to liver cirrhosis were subjected to multivariate logistic regression analysis." (PMID 23990947, 2013).
lung carcinoma (4 papers, 2019 to 2023). "Thus, STAT4 activation causes CFH overexpression that allows lung cancer cells to escape from complement-mediated immune system attack." (PMID 30987235, 2019). "STAT4 overexpression in lung cancer leads to overexpression of CFH, which then mediates inadequate therapy response." (PMID 34638338, 2021). "STAT4 regulates complement factor H (CFH) in lung cancer, which inhibits the complement system and mediates resistance to therapy with monoclonal antibodies, which generally enhances complement activation leading to cellular cytotoxicity." (PMID 34638338, 2021). "Instead, differential methylation was found on the regulatory region of STAT4 between normal and lung cancer cells." (PMID 30987235, 2019). "Altogether, this result revealed that CFH overexpression in A549 cells and lung cancer tissue is under the control of STAT4 activation, which is known to be mediated by the JAK and SOCS cytokine signaling pathway." (PMID 30987235, 2019). "First, signal transducer and activator of transcription 4 (STAT4) expression patterns coincided with CFH expression patterns in lung cancer tissues." (PMID 30987235, 2019). "In the present study, lower methylation was found in A549 lung cancer cells than in L132 normal cell lines, which is reversely consistent with higher STAT4 RNA expression in A549 than in L132 cells." (PMID 30987235, 2019). "We have shown that STAT4 is responsible for the upregulation of CFH in lung cancer cells." (PMID 30987235, 2019). "In conclusion, our results highlighted that CFH overexpression in lung cancer is due to the demethylation of the STAT4 regulatory region, resulting in its over expression, which may be activated by the JAK/STAT pathway negatively controlled by SOCS-1 proteins." (PMID 30987235, 2019). "Our results showed the presence of phosphorylated STAT4 in lung cancer cells." (PMID 30987235, 2019). "Our study demonstrated that STAT4 stimulates CFH upregulation in lung cancers." (PMID 30987235, 2019). "Knockdown of STAT4 led to decreased CFH secretion from lung cancer cells." (PMID 30987235, 2019). "Therefore, we hypothesized that overexpression of CFH in lung cancer is the result of upstream factors that are involved in cytokine signaling, dysregulating the activity of STAT4." (PMID 30987235, 2019). "We also showed that phosphorylated STAT4 and CFH expression were decreased by STAT4 knockdown, indicating that CFH expression levels are regulated by STAT4 in lung cancer." (PMID 30987235, 2019). "Next, to investigate any correlation between CFH expression and the expression of STATs in human normal lung tissues and lung cancer tissues, the transcription level of CFH was compared with STAT1, STAT3, and STAT4." (PMID 30987235, 2019). "Hypomethylation of the STAT4 regulatory region can activate the JAK/STAT4 pathway, resulting in CFH overexpression in lung cancers." (PMID 30987235, 2019). "In conclusion, our results demonstrated that CFH is upregulated by constitutive activation of STAT4, which is accounted for by SOCS silencing in lung cancer cells." (PMID 30987235, 2019). "We demonstrated that CFH expression levels are highly correlated with STAT4 expression levels in human lung cell lines and human lung cancer tissues without any stimuli." (PMID 30987235, 2019).
parasitemia (4 papers, 2019 to 2023). "As expected, inoculation of either STAT-1−/− or STAT-4−/− mice with WT parasites resulted in high levels of parasitemia and death of 100% of the mice between 15-23 days post-infection (for STAT-1−/−) or 21–62 days for STAT-4−/− mice." (PMID 37185599, 2023). "However, the expression of IL-2, IL-12, IFN-γ, together with that of specific transcriptional factors (STAT1 and STAT4) is suggestive of a Th1-like polarization, induced after parasite infection." (PMID 35632559, 2022). "IL-12 and STAT4 are implicated in the regulation of NK cell IL-10 production during certain parasitic infections, but are not required for this response during Lm infection." (PMID 31552035, 2019). "Interestingly, infection of STAT6- but not STAT4-knockout mice with this same (Brazil) strain resulted in decreased parasitemia, inflammation, and mortality when compared with wild-type mice." (PMID 32626662, 2020).
polymyositis (4 papers, 2014 to 2024). A rare idiopathic inflammatory myopathy characterized by symmetric proximal muscle weakness and elevated muscle enzymes. "An additive effect of both risk alleles (the C8orf13–BLK rs13277113A allele and the STAT4 rs7574865 T allele) on susceptibility to polymyositis, dermatomyositis, and polymyositis/dermatomyositis was observed." (PMID 24632671, 2014). "The C8orf13–BLK rs13277113 A and STAT4 rs7574865 T alleles had an additive effect on polymyositis/dermatomyositis susceptibility." (PMID 24632671, 2014). "We have previously reported STAT4 rs7574865 is associated with susceptibility to polymyositis/dermatomyositis in Japanese." (PMID 24632671, 2014). "Both C8orf13–BLK and STAT4 additively increased polymyositis/dermatomyositis susceptibility in the Japanese population." (PMID 24632671, 2014). "C8orf13–BLK rs13277113A and STAT4 rs7574865T exert additive effects in polymyositis/dermatomyositis susceptibility." (PMID 24632671, 2014). "A possible gene–gene interaction between C8orf13–BLK and STAT4, which we recently showed to be associated with Japanese polymyositis/dermatomyositis, was also analyzed." (PMID 24632671, 2014). "A cumulative effect of risk allele number (C8orf13–BLK rs13277113A and STAT4 rs7574865T) on susceptibility to polymyositis, dermatomyositis, and polymyositis/dermatomyositis." (PMID 24632671, 2014). "Four non‐HLA regions reached genome‐wide significance, SDK2 and LINC00924 (both novel) and STAT4 in the whole IIM cohort, with evidence of independent variants in STAT4, and NAB1 in the polymyositis (PM) subgroup." (PMID 36580032, 2023). "In this study, we investigated whether C8orf13–BLK variants contribute to disease susceptibility in Japanese polymyositis/dermatomyositis patients and assessed any potential additive effects between C8orf13–BLK and STAT4 in the susceptibility to polymyositis/dermatomyositis." (PMID 24632671, 2014).
prostate carcinoma (4 papers, 2017 to 2024). A carcinoma that arises from epithelial cells of the prostate gland. "Intrigued by the nexus between cytokine signalling and transcriptional control, we postulate that the IL-11 autocrine loop is a determinant of docetaxel resistance in prostate cancer via the JAK1/STAT4 signalling axis." (PMID 38429845, 2024). "We further evaluated the compensatory effects of STAT4 overexpression in prostate cancer cell lines PC3 and DU145 with reduced IL-11 signalling." (PMID 38429845, 2024). "Other scholars have also demonstrated that STAT4 can increased the expression of PD-1, enhancing the anti-cancer efficacy of immune checkpoint inhibitor therapy in prostate cancer." (PMID 38774752, 2024). "We chose to investigate this in DU-145 prostate cancer-derived cells, because they functionally express all STATs, except STAT4, which is predominantly expressed in lymphocytes." (PMID 28903353, 2017). "The potential to overcome resistance by inhibiting the IL-11/IL-11RA/JAK1/STAT4 axis may represent a paradigm shift in prostate cancer treatment." (PMID 38429845, 2024). "Parallel changes were noted in STAT family proteins, with STAT4 in particular demonstrating a significant response to IL-11 modulation, thereby reinforcing the connection between IL-11 signalling and STAT4-mediated transcriptional regulation in prostate cancer." (PMID 38429845, 2024). "In the prostate cancer cell lines PC3 and DU145, IL-11 treatment significantly increased levels of phosphorylated STAT4, indicative of its activation." (PMID 38429845, 2024). "Notably, upon neutralization of IL-11 signalling using an IL-11 antagonist, the expression and phosphorylation levels of JAK1 and STAT4 were markedly altered, substantiating the pivotal role of IL-11 in activation of the JAK/STAT pathway in prostate cancer." (PMID 38429845, 2024).
pulmonary TB (4 papers, 2015 to 2024). "In addition, the impact of STAT4 polymorphisms appears to be more pronounced in young patients with pulmonary tuberculosis (PTB)." (PMID 39575235, 2024). "To date, three studies have been conducted to investigate the relationship between STAT4 polymorphisms and TB, and one of them demonstrated that STAT4 promoter region polymorphisms were associated with pulmonary TB (PTB) and may impact STAT4 expression." (PMID 30054428, 2018). "In addition, the polymorphisms of STAT4 promoter-region were reported to be associated with pulmonary TB in a Moroccan population, which might impact STAT4 expression." (PMID 26626589, 2015). "In the present study, we have investigated the association between STAT4 polymorphisms and a predisposition to Mycobacterium tuberculosis (MTB) infection and pulmonary tuberculosis (PTB)." (PMID 30054428, 2018). "A study revealed an association between STAT4 SNPs (rs6752770, rs3024861, rs7572482, rs1031509, rs1400654 and rs897200) and PTB, particularly highlighting a strong correlation between rs897200 and younger PTB patients (pulmonary tuberculosis onset <25 years)." (PMID 39575235, 2024).
ulcerative colitis (4 papers, 2010 to 2023). An inflammatory bowel disease involving the mucosal surface of the large intestine and rectum. "Ulcerative colitis is also linked to rs3024493, within intron 3; this is 1 k upstream of BRG1, STAT4 and CBP binding at +3.2 k, and slightly downstream of BRG1 binding and H3K9 acetylation at +1.8 k." (PMID 22336179, 2012).
antiphospholipid syndrome (3 papers, 2012 to 2025). A disorder caused by the presence of autoantibodies directed against phospholipids, causing a hypercoaguable state, which may result in blood clots, stroke, heart attack, and in women, significant pregnancy-related complications, including miscarriage and still birth. "A meta-analysis further implicates the STAT4 rs7574865 T-allele in the increased risk of SSc and antiphospholipid syndrome." (PMID 40831950, 2025). "The STAT4 G > T (rs7574865) SNP has also been associated with antiphospholipid syndrome in Italian cohorts, as has the production of anti-Sm antibodies in a Northern Han Chinese population." (PMID 22729903, 2012). "Recent reports have confirmed the additive effects of STAT4 and IRF5 SNPs which may increase the risk of SLE and antiphospholipid syndrome." (PMID 31871930, 2019).